ENSG00000238645
Synonyms: LOC124903784
Gene: Small nucleolar RNA gene on chromosome 16 (53,334,562 to 53,334,664, forward strand). Ensembl gene ENSG00000238645.
Gene Ontology:
Biological process: RNA processing
Cellular component: nucleolus
Homologues: Paralogues in human: SNORD13 (91% identical), SNORD13P1 (90% identical), SNORD13P3 (88% identical), SNORD13E (85% identical), SNORD13D (83% identical).